TLR7 (toll like receptor 7)
Diseases named in the same sentence as TLR7 in open-access papers (continued):
Sharing a sentence is not in itself a finding about the gene and the disease.
allergic rhinitis (8 papers, 2012 to 2024). Inflammation of the nasal mucous membranes caused by an IgE-mediated response to external allergens. "Several studies have investigated the TLR7 rs864058 polymorphism in various respiratory diseases, such as allergic rhinitis, measles infection, and prostate cancer." (PMID 38066751, 2023). "In these studies we demonstrate that repeated intranasal TLR7 stimulation is associated with reduced responsiveness to allergen in patients with allergic rhinitis." (PMID 22726593, 2012). "We conclude that repeated intranasal stimulation of TLR7 by AZD8848 has a potential to affect the immune system in a way that may result in a sustained reduction in the responsiveness to allergen in allergic rhinitis." (PMID 22726593, 2012). "Repeated intranasal stimulation of Toll-like receptor 7 by AZD8848 was safe and produced a sustained reduction in the responsiveness to allergen in allergic rhinitis." (PMID 22726593, 2012). "Another placebo‐controlled trial showed that repeated intranasal TLR7 agonist AZD8848 reduced symptoms in patients with birch and/or grass pollen allergic rhinitis, but it produced reversible blood lymphocyte reduction and dose‐dependent flu‐like symptoms as side‐effects." (PMID 26061394, 2015). "Our observations extend recent in vitro and animal reports on anti-allergic effects of AZD8848, indicating that repeated TLR7 stimulation reduces the responsiveness to allergen, and suggest that AZD8848 may be clinically effective in allergic rhinitis." (PMID 22726593, 2012).
endothelial dysfunction (8 papers, 2012 to 2025). In vascular diseases, endothelial dysfunction is a systemic pathological state of the endothelium (the inner lining of blood vessels) and can be broadly defined as an imbalance between vasodilating and vasoconstricting substances produced by (or acting on) the endothelium. "The persistent activation of pattern recognition receptors, particularly TLR7, is associated with both chronic inflammation and endothelial dysfunction." (PMID 41012652, 2025). "Recently, it has been proven that TLR7 activation causes endothelial dysfunction and hypertension, and further underscored the augmented vascular inflammation and oxidative stress, facilitated partially by IL-17, as crucial elements conducive to cardiovascular complications." (PMID 34444829, 2021). "In conclusion, gut microbiota plays a role in the TLR7-driven increase in Th17 cell, endothelial dysfunction, vascular inflammation, and hypertension." (PMID 34573058, 2021). "Nonetheless, excessive activation of placental TLR7/8 is sufficient to induce pregnancy-dependent hypertension and endothelial dysfunction similar to that induced by TLR3 activation." (PMID 22848646, 2012). "Overall, our data suggest that endothelial dysfunction induced by TMAO under TLR7 activation is mainly mediated by vascular Th17 infiltration, and the subsequent ROS levels increased, linked to increased NADPH oxidase-driven ROS production and reduced nrf2 antioxidant defense." (PMID 35052589, 2021). "It has already been shown that gut microbiota, independently of SCFA production, contributes to the TLR7-driven raise in Th17 cells, kidney damage, endothelial dysfunction, vascular inflammation, and hypertension, and probiotics consumption decreased BP under TLR7 activation conditions." (PMID 35052589, 2021).
esophageal cancer (8 papers, 2019 to 2025). A primary or metastatic malignant neoplasm involving the esophagus. "For example, in esophageal cancer, increased expression of TLR3, TLR4, TLR7, and TLR9 has been linked to esophageal squamous cell carcinomas, while TLR1, TLR2, TLR4, and TLR6 are often overexpressed in esophageal adenocarcinoma." (PMID 40109582, 2025). "In esophageal cancer TLR3 was associated with invasion and lymph node metastasis, TLR4 with lymph node metastasis and TLR7 with worse histological grade." (PMID 38709790, 2024). "Another study demonstrated that exosomal FMR1-AS1 played a role in maintaining the dynamic interconversion state of cancer stem-like cells in female esophageal carcinoma through the activation of the TLR7-NFκB signaling axis." (PMID 36133437, 2022). "Exosomal FMR1-AS1 is involved in maintaining the dynamic interconversion balance of cancer stem cell-like cells in female esophageal cancer (ESCC) through the TLR7/NFκB/c-Myc signaling pathway by activating TLR7-NFκB signaling and upregulating c-Myc levels in receptor cells." (PMID 36365103, 2022). "Moreover, patients with esophageal cancer and lymph node metastases had higher TLR-4 levels in tumor tissues, and in the subgroup with esophageal-gastric junction adenocarcinoma, significantly higher expression of TLR-7 mRNA and TLR-4, TLR-7, and TLR-9 proteins was observed." (PMID 39451226, 2024).
glioblastoma (8 papers, 2009 to 2025). The most malignant astrocytic tumor (WHO grade IV). "In sum, sustained local TLR7/8 agonism within the context of tumor resection is a promising approach for glioblastoma." (PMID 39399681, 2024). "Additionally, clinical studies in glioblastoma have demonstrated that the application of TLR7/8 agonists combined with GSM DHCR7/cholesterol signaling modulation significantly promotes the polarization of glioblastoma stem-like cells (GSMs) toward an anti-tumor phenotype and improves the TME." (PMID 41488647, 2025). "This latter exerts a tumor suppressive function by inhibiting proliferation and malignancy of glioblastoma cells by targeting both NRAS and KRAS and by modulating microglia activation through TLR7." (PMID 33287106, 2020). "Synthetic siRNA duplexes have now been show to activate PKR in glioblastoma cells, RIG-I in glioblastoma cells and primary human monocytes, TLR3 in HEK293 cells and murine models, TLR7 in murine leukocytes and human plasmacytoid dendritic cells, and TLR8 in human monocytes." (PMID 19630977, 2009).
Klinefelter syndrome (8 papers, 2019 to 2024). A sex chromosome disorder caused by the presence of an extra X chromosome in the male karyotype. "Recently, it was demonstrated that the gene encoding TLR8, which is closely located to Tlr7, also escapes X-chromosome inactivation in immune cells in women and Klinefelter syndrome men." (PMID 38791389, 2024). "Actually, biallelic expression of TLR7 has been found in primary B lymphocytes, monocytes, and plasmacytoid dendritic cells (pDCS) of women (and Klinefelter syndrome males) and this results in higher TLR7 protein expression in leukocyte populations of females." (PMID 32774170, 2020). "Stimulated PBMCs from females and Klinefelter syndrome patients exhibited significantly higher expression level of TLR7 compared to PBMCs from male and Turner syndrome patients." (PMID 33297945, 2020). "Others have reported that TLR7 is biallelically expressed in female and Klinefelter's syndrome male primary monocytes and B cells and our data confirmed that TLR7 was increased in male vs. female monocytes similar to CXorf21." (PMID 31695690, 2019). "The Tlr7 gene is located on the X chromosome and the risk of developing SLE correlates with the number of X chromosomes an individual carries, demonstrated by the female predominance and increased incidence in men with Klinefelter syndrome (47, XXY)." (PMID 38791389, 2024). "The close proximity between the two genes, and the homology and similarity of function between the encoded receptors, warranted investigating whether TLR8, mirroring TLR7, could be transcribed on the inactive X chromosome (Xi) of the immune cells of women and Klinefelter syndrome men." (PMID 37723501, 2023). "We unequivocally demonstrated that TLR8, like TLR7, escapes XCI in immune cells from female and Klinefelter syndrome males." (PMID 37723501, 2023). "In a previous study, we established TLR7 escape from XCI in monocytes from four 47,XXY men with Klinefelter syndrome (KS)." (PMID 37723501, 2023). "X-chromosome inactivation normally contributes to the silencing of one arbitrary X chromosome, but not all genes are affected, and it has been shown that Tlr7 escapes X-chromosome inactivation in B cells, monocytes, and pDCs in both women and Klinefelter syndrome men." (PMID 38791389, 2024).
leukemia (8 papers, 2015 to 2023). A malignant (clonal) hematologic disorder, involving hematopoietic stem cells and characterized by the presence of primitive or atypical myeloid or lymphoid cells in the bone marrow and the blood. "Infectious ERVs emerge in mice deficient in Toll-like receptor 7 (TLR7), and re-integration of these ERVs in the genome can cause leukemia in TLR3/7/9-deficient mice." (PMID 35058919, 2021). "Vaccination of high‐risk AML patients with TLR7/8‐matured RNA‐loaded DCs was feasible, safe and resulted in induction of leukaemia‐specific immune responses." (PMID 32153780, 2020). "In this first‐in‐human phase I trial, TLR7/8‐matured DCs transfected with RNA encoding two leukaemia‐associated antigens (WT1 and PRAME) and CMVpp65 were used as post‐remission therapy for AML patients at high risk of relapse." (PMID 32153780, 2020). "Among the TLRs measured, TLR7 was found to be highly expressed in the bone marrow of the adult koala that died with leukemia; however, TLR13 was undetectable in the bone marrow (with 4.15 nanogram RNA)." (PMID 33915914, 2021). "As previous study indicated the activation of TLR7 increased the leukemia cells and led to the immune rejection." (PMID 25654296, 2015). "Moreover, further studies on the effect of TLR7/8 agonist on the metabolism of other types of leukemia will be of great value." (PMID 37786827, 2023). "In leukemia research, activation of TLR7 by R848 could increase the immunogenicity of acute myeloid leukemia cells and result in the rejection of these cells by host immune response." (PMID 25654296, 2015). "In the treated and later infected groups, there was increased expression of TLR7 and CCR4, a chemokine receptor predominantly expressed by Th2 cells and related to inflammatory diseases and T cell neoplasms, such as leukemias and lymphomas." (PMID 36357780, 2022). "Both TLR-7 and TLR-9 ligands are equally efficient to stimulate ivD-pDC and induce NK cell anti-leukemia activity." (PMID 28555259, 2017).
myocarditis (8 papers, 2017 to 2025). Myocarditis is a condition that is characterized by inflammation of the heart muscle (myocardium). "During acute CVB3-induced myocarditis most of the plasma membrane and intracellular localized TLRs showed an enhanced gene expression, however, Tlr2, Tlr3, Tlr6, Tlr7, and Tlr9 displayed by far the highest increase of mRNA expression during acute disease." (PMID 29538462, 2018). "Additionally, TLR7 knockout mice are protected against myocarditis following the induction of autoimmune myocarditis." (PMID 39828779, 2025). "Contradictory evidence suggests that it could also have pro-inflammatory properties, as extracellular miR-146a-5p can induce myocardial inflammation in murine hearts via the toll-like receptor 7 (TLR7)." (PMID 41008658, 2025). "TLR1, TLR2, and TLR7 are overexpressed on mRNA level in patients with myocarditis." (PMID 35514979, 2022). "TLR7 activation contributes to systemic inflammation, myocarditis and dilated cardiomyopathy." (PMID 34639145, 2021). "TLR7 preferentially promotes the differentiation of Th17 cells and the expression of inflammatory factors, such as IL-17 after CVB3 infection, while TLR8 promotes the production of Th1 cytokines and IFN-α/β response, which are involved in the pathogenesis of myocarditis." (PMID 35514979, 2022).
bronchiolitis (7 papers, 2012 to 2017). Inflammation of the bronchioles characterized by swelling of the bronchioles and mucus accumulation. "We have previously shown that TLR7 deficiency predisposes mice to severe PVM bronchiolitis and an IFN-αlow, IL-33high cytokine microenvironment." (PMID 28099113, 2017). "Among the nine studied TLRs, only TLR7 rs179008 showed some exploratory associations with post-bronchiolitis lung function deficiency, and polymorphisms of TLR4 rs4986790, and TLR6 rs5743810 in particular, with airway reactivity." (PMID 26741133, 2016). "Instead, the presence of the minor allele T in the TLR7 rs179008 gene in males was associated with the RSV aetiology of bronchiolitis (100% vs. 70.4% in those with the major allele A) and with the need for feeding support (54.5% vs. 24.1%, respectively)." (PMID 27498757, 2016). "Interestingly, TLR7−/− mice that had developed severe viral bronchiolitis in early-life were also at greater risk of sensitization to a bystander allergen." (PMID 28539639, 2017). "Our study was an exploratory study on the possible association between the TLR7 rs179008, TLR8 rs4207992, TLR9 rs187084 or TLR10 rs4219009 gene polymorphisms and characteristics of bronchiolitis in early infancy or post-bronchiolitis outcomes." (PMID 27498757, 2016). "Presence of TLR7 rs179008 major allele A and baseline IOS results (z-scores) and exercise-induced changes (z-scores) in the 50 former bronchiolitis cases who were girls." (PMID 26741133, 2016). "The aim of this exploratory study was to evaluate whether there are associations between TLR7 rs179008, TLR8 rs2407992, TLR9 rs187084 or TLR10 rs4129009 polymorphisms and viral findings, clinical characteristics or subsequent wheezing in infants with bronchiolitis." (PMID 27498757, 2016). "The aim of the present study was to complement this exploratory study series by evaluating whether the TLR7 rs179008, TLR8 rs2407992, TLR9 rs187084 and TLR10 rs4129009 polymorphisms are associated with the presence, clinical characteristics and viral etiology of bronchiolitis in early infancy." (PMID 27498757, 2016). "TLR7 rs179008 genotypes and baseline IOS (z-scores) and exercise-induced changes (z-scores) in the 50 former bronchiolitis cases who were girls." (PMID 26741133, 2016). "TLR-7 recognizes single-stranded RNA (viral); TLR-7 mRNA is increased in infants with naturally-occurring RSV compared to infants with non-RSV bronchiolitis." (PMID 23202468, 2012).
chronic hepatitis B (7 papers, 2017 to 2025). "In this review, we summarize the recent advances in the development of immunotherapy strategies targeting TLR7/8 in patients with various cancers and chronic hepatitis B." (PMID 36476317, 2022). "Specific and prolonged suppression of chronic hepatitis B in chimpanzee and woodchuck models by endosomal TLR7, 8, and 9 agonists led to an interest in discerning the mechanisms by which these TLR ligands elicit antiviral responses." (PMID 32728070, 2020). "In the current study, we have shown that TLR7 expression is reduced in liver biopsy samples of Chronic Hepatitis B patients compared to steatosis individuals serving as disease controls." (PMID 28088184, 2017). "By activating the TLR7 signaling pathway, GS-9620 induces the production of cytokines such as interferon and inhibits the replication of hepatitis B virus, and is being studied as a therapeutic option for chronic hepatitis B." (PMID 41568029, 2025). "Given that observation in addition to the knowledge that IFN-α induction by TLR7 agonists is of high interest during chronic hepatitis B virus infection, conjugation of TLR7-ligands to cholesterol could be a therapeutical approach." (PMID 35126343, 2021).
Erythema (7 papers, 2019 to 2025). Redness of the skin, caused by hyperemia of the capillaries in the lower layers of the skin. "Application of imiquimod, a TLR7 agonist, to mouse skin leads to the development of psoriatic features, such as epidermal thickening, erythema, inflammatory cell infiltration, and epidermal expression of IL-17." (PMID 34575956, 2021). "Moreover, the capacity of TLR7, which binds IMQ, to be desensitized over repetitive stimulations, could also be a possible explanation for reduced erythema, epidermal hyperplasia and skin barrier function disruption in LT treatment compared to ST treatment." (PMID 40702143, 2025).
Hypertension (7 papers, 2012 to 2024). The presence of chronic increased pressure in the systemic arterial system. "Recently, we demonstrated that TLR7 activation causes hypertension and vascular damage in BALB/c mice, and emphasizes the elevated vascular inflammation and oxidative stress, mediated in part by interleukin (IL)-17, as crucial factors for cardiovascular complications." (PMID 34573058, 2021). "Recently, it has been shown that TLR7 initiates vascular dysfunction and hypertension in BALB/c mice." (PMID 35052589, 2021). "We proceeded to study the gut microbial community composition derived from both antibiotic treatments, to assess potential pathobionts regulating TLR7-dependent hypertension." (PMID 34573058, 2021). "Taken into account that higher autoantibodies production by B cells and Th17 infiltration in vascular tissues were key events in the development of hypertension induced by TLR7 activation we estudied the changes in immune cells induced by both probiotics." (PMID 34444829, 2021). "Furthermore, increased vascular inflammation and oxidative stress, mediated in part by IL-17, as key factors contributing to hypertension in this TLR7-driven lupus autoimmunity model." (PMID 34444829, 2021). "In our experiment, LC40 or BFM administered to IMQ mice prevented the raise of blood pressure, suggesting that changes in gut microbiota might influence the mechanisms involved in the development of hypertension induced after TLR7 activation." (PMID 34444829, 2021). "We then studied the mechanisms involved in TMAO-induced, TLR7-dependent hypertension." (PMID 35052589, 2021). "This hypertension was validated by the FCM results, which indicated that the percentage of TLR7-expressing cells was increased in the isolated hepatic lymphocytes." (PMID 34692568, 2021). "Notably, we have reported that the gut microbiota plays a role in the development of hypertension in both female NZBWF1 mice and SLE mice induced by TLR7 activation." (PMID 38137363, 2023).
liver cancer (7 papers, 2016 to 2023). An epithelial or non-epithelial malignant neoplasm that arises from the liver. "Furthermore, HCC exhibits a high number of rafts that can participate in the promotion of liver cancer cell proliferation and migration by up-regulating toll-like receptor 7 (TLR7) expression." (PMID 37108625, 2023). "Another two studies reported that IRS-954, an inhibitory DNA sequence against TLR7 and 9, and chloroquine, which inhibits TLR7 and 9 activation, significantly impeded tumor development and growth in vivo and in vitro in liver cancer and cholangiocarcinoma models." (PMID 36479129, 2022). "TLRs are upregulated in HCC tissues, and inhibition of TLR7 and TLR9 eliminates the proliferation of liver cancer cells." (PMID 33915844, 2021).